BMP7 (bone morphogenetic protein 7)
Diseases named in the same sentence as BMP7 in open-access papers (continued):
Sharing a sentence is not in itself a finding about the gene and the disease.
sirenomelia (3 papers, 2012 to 2024). Sirenomelia is a rare, genetic, developmental defect during embryogenesis disorder characterized by fusion of the lower limbs and associated with some degree of lower extremity reduction and persistent vitelline artery. "Here, we report that the removal of one or both functional alleles of Shh from the Bmp7-null background leads to a sirenomelia phenotype that faithfully replicates the constellation of external and internal malformations, typical of the human condition." (PMID 23028704, 2012). "The milder sirenomelia phenotype of Bmp7−/−;Shh+/− mutants, although associating major visceral defects in the urogenital and low intestinal tracts, exhibits a normal development of the sacrum and tail." (PMID 23028704, 2012). "In the context of other studies on limb development we found that the reduction of one or both Shh functional alleles from the Bmp7-null background led to sirenomelia." (PMID 23028704, 2012). "Indeed, loss of a single copy of Bmp4 and both copies of Bmp7 in Bmp4flox/+Bmp7flox/flox compound mutant mice (Hoxa3-Cre;Bmp4flox/+Bmp7flox/flox) resulted in hindlimb fusion as well as loss of the bladder and anal stenosis, essential diagnotic features of sirenomelia (n = 3)." (PMID 23028455, 2012). "The implication of Bmp signaling in sirenomelia came from the observation that the double Bmp7;Tsg (Twisted gastrulation) mutant mouse displayed this malformation." (PMID 23028704, 2012). "Bmp7−/−;Shh+/− mutants, in which one functional copy of Shh remains, displayed a milder form of sirenomelia with about 50% penetrance (11 out of 21 neonates)." (PMID 23028704, 2012). "The sirenomelia of Bmp7−/−;Shh+/− mutants can be classified as Type I of Stocker and Heifetz classification." (PMID 23028704, 2012). "The finding that Bmp7−/−; Shh+/− mutants, which display sirenomelia, only showed a minimal increase in cell death intensity suggests that abnormal cell death or proliferation are not a major cause for the phenotype." (PMID 23028704, 2012). "The skeletal preparations, in comparison with wild type, demonstrated that the single medial hindlimb typical of the severe sirenomelia of double homozygous (Bmp7−/−; Shh−/−) was the result of the fusion of two independent hindlimbs." (PMID 23028704, 2012). "The similarity of the sirenomelia phenotype of our mutants and that of Bmp7;Tsg mutants suggest a common origin." (PMID 23028704, 2012). "From these crosses, the sirenomelia phenotype was found restricted to embryos and neonates with the Bmp7−/−;Shh−/− and Bmp7−/−;Shh+/− genotypes." (PMID 23028704, 2012). "Unfortunately, the low penetrance and early embryonic lethality of Bmp7;Tsg and of Cyp26a1 mutants exclude them as suitable models of human sirenomelia." (PMID 23028704, 2012). "Thus, the spectrum of visceral malformations exhibited by Bmp7−/−;Shh−/− and Bmp7−/−;Shh+/− mutants faithfully recapitulates that reported in human cases of sirenomelia." (PMID 23028704, 2012). "Finally, it should be stressed that, the mild sirenomelia of Bmp7−/−;Shh+/− occurs with a normal development of the sacrum and tail." (PMID 23028704, 2012). "Thus, the possibility that Shh function is reduced in Bmp7;Tsg sirenomelia mutants should be explored." (PMID 23028704, 2012). "Therefore, the removal of one or both copies of Tsg from the Bmp7 background further reduces Bmp signaling resulting in caudal abnormalities and sirenomelia." (PMID 23028704, 2012). "Here we identify and characterize the sirenomelia phenotype in Bmp7;Shh compound mutants." (PMID 23028704, 2012). "Our results show a genetic interaction between Bmp7 and Shh that results in a spectrum of phenotypes including leg fusion and visceral malformations that are morphologically identical to human cases of sirenomelia." (PMID 23028704, 2012).
sirenomelia (continued). "We show that Bmp7−/−;Shh−/− and Bmp7−/−;Shh+/− mutants conjointly replicate the constellation of external and internal malformations in the human condition and thus we propose these mutants as the most suitable animal model for human sirenomelia to date." (PMID 23028704, 2012). "Bmp7 KO mice do not show sirenomelia phenotypes, but display kidney hypoplasia; implying possible functional redundancy of BMP signaling." (PMID 23028455, 2012). "Interestingly, Bmp7+/−;Shh−/− displayed a phenotype indistinguishable from that of Shh−/− mutants that do not display sirenomelia (not shown) indicating that the dose of Bmp7 is the limiting factor for the this malformation." (PMID 23028704, 2012).
virus infection (3 papers, 2016 to 2024). "It was interesting to note that CCL27 and BMP7 are down in the acute phase of viral infection as this may result in amplified virus infection." (PMID 37831367, 2024). "Notably, the BMP-7 expression was decreased in model SD rats and those with Lenti-si-NC virus infection, compared to normal SD rats, but restored in model SD rats infected with lenti-si-Gremlin1 virus." (PMID 27863390, 2016). "Other metabolic factors, including FGF21, BMP7, and GDF15, trended up upon virus infection, presumably due to a compensatory effect as these three secreted proteins were involved in positively maintaining metabolic homeostasis." (PMID 34916489, 2021).
aortic stenosis (2 papers, 2021). Aortic valve stenosis is a aortic valve disease caused by the incomplete opening of the aortic valve. "In patients with aortic stenosis, and mice subjected to transverse aortic constriction, pressure overload resulted in decreased levels of BMP7 and pSmad1/5/8 (the intracellular effectors of BMP7) and an increase in TGF-β and pSmad2/3." (PMID 34690762, 2021).
atrial fibrillation (2 papers, 2022 to 2024). A disorder characterized by an electrocardiographic finding of a supraventricular arrhythmia characterized by the replacement of consistent P waves by rapid oscillations or fibrillatory waves that vary in size, shape and timing and are accompanied by an irregular ventricular response. "This interaction allows BMP-7 to counteract fibrosis in myocardial fibroblasts that occur due to atrial fibrillation." (PMID 39335642, 2024). "In a mouse model of atrial fibrillation (AF), BMP-7 has been shown to protect cardiac functions." (PMID 39335642, 2024). "A small subgroup of CKD patients with atrial fibrillation (n = 5) showed a significant BMP-2/BMP-7 imbalance with significantly higher (p < 0.05) BMP-2 and lower (p < 0.07, non-significant) BMP-7 concentrations compared with CKD patients without atrial fibrillation." (PMID 36613483, 2022).
Autoimmunity (2 papers, 2016 to 2022). The occurrence of an immune reaction against the organism's own cells or tissues. "Both NK activation and autoimmunity are linked to BMP signaling, e.g., via an autocrine activation pathway via BMP receptors and BMP ligands in NK cells, which fits our identified target genes BMP1, BMP2, BMP3, BMP7, BMP6, BMPER, BMPR1B, and, most importantly, BMPR2." (PMID 35455956, 2022).
basal cell carcinoma (2 papers, 2013 to 2015). A carcinoma involving the basal cells.
bone fracture (2 papers, 2022). "Only BMP-2 (Infuse® bone graft) and BMP-7 (OP-1 putty®), also known as osteogenic protein 1 (OP-1), have been approved by the FDA for the treatment of very specific bone fractures that exhibit delayed or incomplete healing." (PMID 35328773, 2022).
bone metastasis (2 papers, 2011 to 2022). Transfer of a neoplasm from its primary site to bones. "BMP7 expression was also shown to be associated with early bone metastasis." (PMID 22118688, 2011).
calcification (2 papers, 2018 to 2019). Process by which organic tissue becomes hardened by the physiologic deposit of calcium salts. "In the present study it was examined whether BMP7 treatment might potentially be able to reverse established uremic vascular calcification (VC) as BMP7 previously has been shown to inhibit development and progression of this condition." (PMID 29304096, 2018).
cervical carcinoma (2 papers, 2023 to 2025). A carcinoma arising from either the exocervical squamous epithelium or the endocervical glandular epithelium. "BMP7 also exhibits high expression levels in cervical cancer, making it a potential therapeutic target for cervical cancer treatment." (PMID 40658678, 2025).
cholangiocarcinoma (2 papers, 2015 to 2020). A carcinoma that arises from the intrahepatic biliary tree (intrahepatic cholangiocarcinoma) or from the junction, or adjacent to the junction, of the right and left hepatic ducts (hilar cholangiocarcinoma). "Bone morphogenetic protein 7 (BMP7) was revealed as a potential inhibitor of EMT induced by TGFβ in thirty liver tissue samples of patients with cholangiocarcinoma." (PMID 26425122, 2015).
clear cell renal carcinoma (2 papers, 2015 to 2023). A malignant epithelial neoplasm of the kidney characterized by the presence of lipid-containing clear cells within a vascular network. "For example, it was previously indicated that SOSTDC1 is significantly down-regulated in clear cell renal carcinoma and over-expression of SOSTDC1 inhibits its proliferation through suppressing BMP-7-induced phosphorylation of Smad-1, -5, and -8, as well as Wnt-3a signaling." (PMID 26378658, 2015).
colon adenoma (2 papers, 2020 to 2024). An adenoma that arises from the colon. "Here, we show that BMP7 expression represents an early event in CRC as confirmed by its presence in colon adenoma and adenocarcinoma." (PMID 31591478, 2020). "Interestingly, BMP7 was found highly expressed in both colon adenoma and adenocarcinoma, suggesting this phenomenon as an early event in cancer." (PMID 31591478, 2020).
colorectal tumor (2 papers, 2013 to 2020). "BMP7 has been reported to be overexpressed by the malignant epithelial cells of some breast and colorectal tumors." (PMID 32117236, 2020).
craniosynostosis (2 papers, 2024 to 2025). Craniosynostosis is defined as the premature fusion of one or more cranial sutures leading to secondary distortion of skull shape resulting in skull deformities with a variable presentation. "GWAS has also identified BMP2 and BMP7 as susceptibility loci for craniosynostosis, further implicating this pathway as an important regulator of suture closure and craniosynostosis." (PMID 38385025, 2024). "In fact, GWASs on non-syndromic craniosynostosis have identified risk SNPs near BMP2, BMP7, BMPER, and DLX5, which overlap with loci identified here, and are directly linked to RUNX26,111–115." (PMID 40087503, 2025). "Many of the variants in BMP signaling components (e.g., SMAD6, BMP2, BMP7) increase the risk of craniosynostosis rather than causing craniosynostosis directly, suggesting that interactions between pathways (namely, BMP and FGF) may contribute to the etiology of this disorder." (PMID 38385025, 2024).
endometriosis (2 papers, 2021 to 2023). The growth of functional endometrial tissue in anatomic sites outside the uterine body. "In view of our results, as well as the results presented above, comparing the BMP7 expression pattern in endometriosis and reproduction, seems to be very difficult." (PMID 37047609, 2023). "With regard to the clinical symptoms of endometriosis, we confirmed a significant increase in BMP7 expression with an increase in pain severity in patients with endometriosis." (PMID 37047609, 2023). "In our work, we focused on assessing the expression of BMP7 mRNA in the eutopic endometrium of women with endometriosis, confirming its significant upregulation compared to the control group." (PMID 37047609, 2023). "As a result of the tests carried out in the peritoneal fluid of women with endometriosis, a statistically significant increase in BMP-7 concentration was found compared to the concentration of this protein among women from the reference group (p < 0.0001)." (PMID 34680408, 2021). "The analysis of the results showed a statistically significant decrease in BMP-7 concentration in the second stage of endometriosis compared to the concentration of this protein among women with the first stage of the disease (p < 0.0001)." (PMID 34680408, 2021). "A statistically insignificant decrease in BMP-7 concentration was also observed in women at stage IV endometriosis compared to the concentration of this parameter in women at stage III of the disease." (PMID 34680408, 2021). "In contrast, a negative statistically significant relationship was observed between the concentrations of ALK-1 receptor in peritoneal fluid and bone morphogenetic protein-7 in women with endometriosis (p < 0.01; R = −0.254)." (PMID 34680408, 2021). "It was observed that, in the fluid of women with stage IV endometriosis, the concentration of BMP-7 was the lowest in comparison to the concentration of this protein among women at stages III, II and I of the disease." (PMID 34680408, 2021). "The average concentration of BMP-7 among women with endometriosis was 0.93 ng/mL (Q1: 0.81 and Q3: 1.46), and in the reference group, this was 0.52 ng/mL (Q1: 0.28 and Q3: 0.59)." (PMID 34680408, 2021). "It was observed that, in the fluid of women with stage IV endometriosis, the concentration of BMP-7 was the lowest, compared to the concentration of this protein in women at stages III, II, and I of the disease." (PMID 34680408, 2021). "A statistically insignificant decrease in BMP-7 concentration was found among women with stage III endometriosis compared to the level of this parameter in the fluid of women at stage II of the disease." (PMID 34680408, 2021). "The analysis of the results demonstrated a statistically significant decrease in BMP-7 concentration at the second stage of endometriosis, compared to the concentration of this protein in women at the first stage of the disease (p < 0.0001)." (PMID 34680408, 2021). "A statistically insignificant decrease in BMP-7 concentration was found in women at stage III endometriosis compared to the level of this parameter in the fluid of women at stage II of the disease." (PMID 34680408, 2021). "In turn, the antagonistic effect of BMP7 fibrogenesis can be abolished by decreasing its expression mediated by miR-542-3p, a recognized regulator of the development of liver fibrosis, a process that also accompanies endometriosis." (PMID 37047609, 2023). "Few studies have assessed the expression of SMAD4 and BMP7 in endometriosis." (PMID 37047609, 2023). "In the eutopic tissue of women with endometriosis, or in the endometrial foci, the expression profile of BMP7 remained unchanged throughout the menstrual cycle, indicating physiological differences in the normal endometrium compared to pathological endometrial tissue." (PMID 37047609, 2023).
endometriosis (continued). "A heterogeneous profile of the expression levels of the studied genes (BMP-7, SMAD4 and CDH1) and miR-52-3p in the ectopic endometrium with respect to its eutopic counterpart suggests the loss of endometrial epithelium phenotype in women with endometriosis." (PMID 37047609, 2023). "The analysis of the expression levels of BMP7, SMAD4, CDH1, and miR-542-3p according to the stage of endometriosis demonstrated a statistically significant increase in the level of BMP7 expression in the group of patients with stage III compared to stage IV endometriosis (p = 0.035602)." (PMID 37047609, 2023). "In addition, disturbances in the distribution of BMP-2 and BMP-7 molecules can be an important factor in the process of decidualization in women with endometriosis." (PMID 34680408, 2021). "The different patterns of BMP7, SMAD4, and CDH1 gene expression in ECE, EUE, and the control endometrium observed by us suggests the loss of the endometrial epithelium phenotype in women with endometriosis and demonstrates their involvement in the pathogenesis and pathomechanism of this disease." (PMID 37047609, 2023). "In addition, the dysregulation of BMP7 expression in the endometrium can alter metabolic pathways, consequently leading to fibrosis and increasing the formation of adhesions with the progression of endometriosis." (PMID 37047609, 2023). "This may also be the reason why relatively few statistically significant results have been obtained with respect to the associations between BMP7, SMAD4, CDH1, and miR-542-3p expression levels and the biochemical parameters and clinical features of endometriosis." (PMID 37047609, 2023). "In our study, BMP7 downregulation was noted in severe vs. moderate endometriosis, which could be related to the fact that this gene is involved in angiogenesis, considered to be one of the pivotal stages in the development of endometriosis." (PMID 37047609, 2023). "Thus, the disturbed expression profile of BMP7 may suggest its indirect involvement in the mechanism of pelvic pain in women with endometriosis." (PMID 37047609, 2023). "Analyzing the results of this study, it can be assumed that the increased concentration of BMP-7, demonstrated in the peritoneal fluid of women with endometriosis, may disturb decidualization, which can adversely affect the fertility of women with endometriosis." (PMID 34680408, 2021). "The aim of this study was to evaluate the expression profile of miR-542-3p and the EMT markers (BMP7, SMAD4, CDH1) in matched eutopic endometrium (EUE) and ectopic endometrium (ECE) samples from women with endometriosis in relation to healthy women." (PMID 37047609, 2023). "A novelty of our work was the analysis of miR-542-3p, BMP7, SMAD4, and CDH1 expression in PBMCs obtained from women diagnosed with endometriosis compared to those obtained from healthy women." (PMID 37047609, 2023). "BMP-2 and BMP-7 and their soluble receptors, ALK-1 and BMPR2, are involved in the formation of endometriosis." (PMID 34680408, 2021). "The aim of the study was to determine the role of soluble bone morphogenetic proteins, BMP-2 and BMP-7, and their receptors, ALK-1 and BMPR2, in the process of the formation and development of endometriosis." (PMID 34680408, 2021). "This may explain the increase in the concentration of BMP-7 in women with stage I endometriosis who do not develop adhesions and significant reduction of the active surface of the endometrium, which occurs in stage IV of the disease." (PMID 34680408, 2021). "BMP7, SMAD4, CDH1, and miR-542-3p expression levels were assessed in PBMCs from endometriosis patients and in PBMCs from patients without endometriosis, who constituted the control group (C2)." (PMID 37047609, 2023).
esophageal cancer (2 papers, 2014 to 2015). A primary or metastatic malignant neoplasm involving the esophagus. "As BMP7 has already been shown to be a marker of tumor progression and metastases development in breast and esophageal cancers, it is worth further exploring the potential of BMP7 as a marker of malignant behavior by analyzing additional malignant PCC cases for its expression." (PMID 26337467, 2015).